EGFR (epidermal growth factor receptor)
Diseases named in the same sentence as EGFR in open-access papers (continued):
Sharing a sentence is not in itself a finding about the gene and the disease.
adenocarcinoma (continued). "The evidence of pleural tags, pleural and liver metastases go along with a higher probability of EGFR mutation in adenocarcinoma patients and air bronchogram is positively associated with Exon-19 deletion mutation." (PMID 28949965, 2017). "EGFR mutations were associated with low- to intermediate-grade adenocarcinomas, and KRAS mutations were associated with the mucinous subtype." (PMID 29065153, 2017). "The IPASS (Iressa Pan-Asia Study) was regarded as the milestone for the clinical application of EGFR TKI, because it was the first randomized clinical trial to compare EGFR-TKI with chemotherapy at first-line treatment for advanced NSCLC with adenocarcinoma." (PMID 29088904, 2017). "Epidermal growth factor receptor tyrosine kinase inhibitor (EGFR-TKI) dramatically change the prognosis of patients with EGFR mutated adenocarcinoma." (PMID 28152008, 2017). "Reported rates of EGFR gene mutation testing in China suggest that only 30% of NSCLC patients with adenocarcinoma are tested for gene aberrations despite more than 40% having EGFR mutations." (PMID 28673332, 2017). "Our study population consisted of patients with advanced-stage (stage IV in 46 out of 48 patients) adenocarcinoma with sensitizing EGFR mutations and all of them were treated with EGFR TKI as their first-line systemic therapy." (PMID 29099855, 2017). "In this study, patients were selected for EGFR mutation testing on the basis of adenocarcinoma histology and advanced disease." (PMID 28367333, 2017). "Among patients with EGFR-mutant adenocarcinoma, younger smokers were associated with shorter OS (P = 0.047)." (PMID 29228697, 2017). "Among HER2-amplified adenocarcinomas, 24 (52.2%) and 3 (6.5%) had EGFR and KRAS mutations, respectively, while 1 (2.2%) showed ALK rearrangement." (PMID 28146588, 2017). "In conclusion, the status of EGFR mutations in adenocarcinomas of the lung is relatively consistent between primary and metastatic sites compared to K-ras mutations." (PMID 27070580, 2016). "We aimed to explore the discordant mutation statuses of EGFR and K-ras between primary tumors and matched brain metastases in adenocarcinomas of lung." (PMID 27070580, 2016). "Patients, especially never smoked females, who were 51–70 years old, and had 1–20 mm stage I adenocarcinomas on the right side were more likely to possess EGFR mutations." (PMID 26739511, 2016). "The subclassification of NSCLC has also become necessary for guiding molecular analyses because EGFR mutations and other driver mutations were preferentially detected in patients with adenocarcinomas." (PMID 26970967, 2016). "EGFR was mutated in 218 adenocarcinoma patients, and among them CEA, Cyfra21-1, SCCA, and NSE increased in 86, 68, 12, and 70 patients, respectively." (PMID 27072585, 2016). "Cyfra21-1 levels (P = 0.032 for disease-free survival [DFS]; P < 0.001 for overall survival [OS]) and clinical stage were identified as independent predictive and prognostic factors in EGFR-mutated adenocarcinoma patients." (PMID 27072585, 2016). "With the development of targeted therapy, adenocarcinoma are classified into subsets, such as epidermal growth factor receptor (EGFR)-mutated type, anaplastic lymphoma kinase (ALK)-rearranged type and ROS1-rearranged type." (PMID 27708233, 2016). "In Japanese patients, approximately 50 and 5% of adenocarcinomas have a mutation in the epidermal growth factor receptor (EGFR) and echinoderm microtubule-associated protein-like 4-anaplastic lymphoma kinase (EML4-ALK) fusion gene, respectively." (PMID 27070423, 2016). "Serum Cyfra21-1 in 27 non-adenocarcinoma EGFR-mutated patients was significantly higher than in 218 EGFR-mutated adenocarcinoma cases (median: 3.91 versus 2.50 ng/ml, P = 0.014)." (PMID 27072585, 2016). "The prevalence of EGFR mutations in patients with adenocarcinomas was 15.4 %, which was practically identical to our findings." (PMID 27655296, 2016).
adenocarcinoma (continued). "Consistently, we observed that only in EGFR-mutated adenocarcinoma patients, elevated Cyfra21-1 was associated with worse DFS and OS." (PMID 27072585, 2016). "Adenocarcinomas with activating mutations of EGFR are responsive to EGFR tyrosine kinase inhibitors (TKIs)." (PMID 27005669, 2016). "Of the adenocarcinomas, 2,295 (46%) tumors had EGFR mutations, 358 (9.2%) had KRAS mutations, and 270 (7.2%) had ALK rearrangements." (PMID 26992209, 2016). "In the study, the VDT in the 33 adenocarcinoma patients with EGFR mutations was longer than that in 36 adenocarcinoma patients with wild-type EGFR (676 vs. 200 days; P = 0.014)." (PMID 27861565, 2016). "NSE levels were higher in adenocarcinoma cases with EGFR-mutations and only within L858R subgroup did NSE level have marginal predictive and prognostic significance." (PMID 27072585, 2016). "Fifty percent of adenocarcinomas with clear cell component (11/22) harbored EGFR mutation, 41 percent (9/22) harbored KRAS mutation and 5 percent (1/22) harbored AKT1 mutation." (PMID 27013585, 2016). "For example, EGFR mutations, which are predominantly found in adenocarcinomas, are a prerequisite for the application of EGFR tyrosine kinase inhibitors." (PMID 27388913, 2016). "These approvals then required the implementation of EGFR mutation testing in routine clinical practice for patients with adenocarcinomas." (PMID 26970967, 2016). "With the emergence of epidermal growth factor receptor tyrosine kinase inhibitors (EGFR-TKIs), the prognosis of adenocarcinoma patients with specific EGFR mutations has significantly improved." (PMID 27825114, 2016). "Univariate analysis by the log-rank test identified that male sex, smoking history, poor performance status (PS), non-adenocarcinoma histology, and EGFR-WT were associated with poor PFS and/or OS." (PMID 27350261, 2016). "Treating advanced adenocarcinoma based on EGFR mutation status has beneficial effects and saves the cost compared to no testing strategy in South Korea." (PMID 27483001, 2016). "In conclusion, Cyfra21-1 is a predictive and prognostic marker in resectable adenocarcinoma patients harboring EGFR mutations, and a prognostic factor in EGFR del19 or L858R group." (PMID 27072585, 2016). "The present study reinforces the use of EGFR tyrosine kinase inhibition (TKI) as a first line treatment of choice for advanced adenocarcinoma of the lung carrying an activating EGFR mutation." (PMID 27032107, 2016). "In recent years, comprehensive molecular studies have identified genomic aberrations leading to activating mutations in cancer drivers, prototypically presented by EGFR mutation, found in 10–50 % of adenocarcinoma patients." (PMID 27495736, 2016). "Cyfra21-1 and CEA exhibit different predictive and prognostic values between EGFR-mutated and wild-type adenocarcinomas, as well as between EGFR mutation subtypes." (PMID 27072585, 2016). "Among patients with stage IV adenocarcinomas, receipt of erlotinib remained significantly lower among smokers and higher among patients with EGFR mutations." (PMID 27294665, 2016). "Among 7 patients whose AXL 3+-expressing adenocarcinomas had “targetable” mutations, only one patient with an EGFR mutation received an appropriate molecular targeted drug for her recurrent disease (Case 2)." (PMID 27100677, 2016). "Patients with advanced adenocarcinomas are currently tested for EGFR mutations, ALK aberrations, and ROS1 in routine clinical practice." (PMID 26970967, 2016). "It is clear that the occurrence of EGFR-TKIs sensitive mutation in non-adenocarcinoma was relatively rare." (PMID 27992557, 2016). "Albeit only among patients with stage IV adenocarcinomas, we found that EGFR-mutant tumors were associated with better survival." (PMID 27294665, 2016). "In our previous immunohistochemical staining for DPD in NSCLC specimens, high DPD expression was significantly correlated with EGFR mutation status and adenocarcinoma with a lepidic pattern." (PMID 27268079, 2016).
adenocarcinoma (continued). "Among patients with known smoking status and adenocarcinoma, the EGFR mutation test was performed in 59.9% of the younger patients and in 56.1% of the older patients." (PMID 27191886, 2016). "Forty-nine out of 54 patients with histologically proven diagnosis of NSCLC (adenocarcinoma or other non-small cell histology) and with an EGFR gene mutation treated in our center between June 2010 and July 2014 were considered eligible." (PMID 27206674, 2016). "Even in 29 families with pure adenocarcinoma histology, only 7 families (24.1%) had identical EGFR mutation status." (PMID 27449093, 2016). "In our study, we analyzed two common genomic alterations in adenocarcinomas of the lung: EGFR and KRAS mutations." (PMID 27145277, 2016). "EGFR overexpression and mutation have been demonstrated in pre-malignant lung epithelium as well as normal bronchial epithelium adjacent to adenocarcinoma." (PMID 27458163, 2016). "Multivariate analysis demonstrated that presence of EGFR mutations and adenocarcinoma histology were significantly associated with increased PD-L1 expression independently of other factors." (PMID 27833557, 2016). "Although EGFR mutation prevalence in some populations is relatively low at about 10% (e.g. 10.1% in Caucasian males and 12.5% in Asian patients with non-adenocarcinoma) screening must still be provided and only be targeted in resource limited settings." (PMID 27738317, 2016). "On a clinical note, our group has previously reported the association between NSCLC adenocarcinoma and positive EGFR mutation status in patients with history of WSE compared to tobacco smoke exposure." (PMID 27098372, 2016). "EGFR mutations in advanced adenocarcinomas are detected in approximately 10–15 % of Caucasian patients and 40–60 % of patients of Southeast Asian ethnicity." (PMID 26970967, 2016). "EGFR mutations were detected more often in acinar (65.7%), papillary (62.3%), and lepidic (59.5%) adenocarcinomas." (PMID 27861565, 2016). "Three patients with adenocarcinoma histology had a mutation of the epidermal growth factor receptor and received additional treatment with erlotinib." (PMID 27255302, 2016). "The current phase II study thus further clarifies the exact impact of erlotinib in Caucasian patients with an EGFR mutation-positive adenocarcinoma, indicating that erlotinib has a similar therapeutic impact in Caucasian as in Asian patients." (PMID 27032107, 2016). "Afatinib is an orally available agent with increased efficacy compared with chemotherapy, making it an attractive option for advanced NSCLC in those with adenocarcinoma and common EGFR mutations." (PMID 27069737, 2015). "Our results also showed the close association between a higher overall response rate and EGFR mutation among adenocarcinoma." (PMID 26720170, 2015). "In this work, we report, for the first time, that GAS5 downregulation is not only associated with adenocarcinoma tumorigenesis and progression but is also associated with primary resistance to EGFR-TKIs, both in vitro and in vivo." (PMID 25925741, 2015). "Most patients with EGFR mutations presented as acinar predominant adenocarcinoma, while patients with EML4-ALK gene fusions tended to present as solid predominant adenocarcinoma." (PMID 26332764, 2015). "Subsequent isolated recurrence within the lung eighteen months later was a pure adenocarcinoma, again with the same identified EGFR mutation." (PMID 26366316, 2015). "This study aims to delineate the clinicopathologic significance of unique miRNAs in adenocarcinomas classified according to major tyrosine-kinase inhibitor sensitive EGFR mutation status." (PMID 26170125, 2015). "For example, 82.49% of the patients analyzed in the present study were diagnosed with adenocarcinomas, which are known to present greater percentage of EGFR mutation rates compared to other types of NSCLC." (PMID 26622815, 2015).
adenocarcinoma (continued). "In our study 10.6% of the examined NSCLC samples displayed EGFR mutations and the respective frequency reached 12.8% in adenocarcinomas in accordance with current results on populations of European descent." (PMID 26208325, 2015). "After waiting for confirmation of positive results by cytology and histology, which were obtained 3–4 days after bronchoscopic examination, the patient was diagnosed as having adenocarcinoma with an EGFR mutation (cT2aN0M1b, stage IV)." (PMID 25591975, 2015). "Four of the 18 patients (22 %) diagnosed with adenocarcinoma were found to be EGFR mutation carriers, and 3 of these patients were treated with prior erlotinib." (PMID 26503609, 2015). "It was also evident that a high prevalence of EGFR mutation is more frequent in smokers, woman, and patients with adenocarcinoma." (PMID 26048754, 2015). "EGFR tyrosine kinase inhibitors can be beneficial in treating adenocarcinoma arising from type 1 CPAM with EGFR-mutation." (PMID 26236529, 2015). "All patients were diagnosed with adenocarcinomas harboring EGFR activating mutations (seven cases of exon 19 deletion, seven cases of L858R in exon 21, and one case of L861Q in exon 21)." (PMID 26572169, 2015). "Presence of the EGFR T790M secondary mutation was confirmed in the post-treatment liver tumour with adenocarcinoma histology." (PMID 26400668, 2015). "Our study results are consistent with previous findings that EGFR mutations were less prevalent in males and smokers and more prevalent in adenocarcinomas." (PMID 26555338, 2015). "EGFR mutations in FFPE tissues were detected in 36 adenocarcinoma patients among 120 NSCLC patients (30.0%) by the PCR-invader method." (PMID 25651992, 2015). "All patients had adenocarcinoma positive for activating EGFR mutations confirmed by a conventional PCR-based method." (PMID 26015401, 2015). "On the other hand, in a young man with a metastatic EGFR mutated adenocarcinoma of the lung the in vitro assay showed a cell mortality of 40% for the combination of oxaliplatin and paclitaxel." (PMID 25955492, 2015). "Use of the EGFR-TKIs erlotinib and afatinib is limited to patients with adenocarcinomas who have known activating EGFR mutations." (PMID 25861506, 2015). "This study aims to delineate the clinicopathologic significance of three unique miRNAs in adenocarcinoma according to major sensitive EGFR mutation status." (PMID 26170125, 2015). "We studied a consecutive series of patients with stage IV NSCLC adenocarcinoma and known EGFR and KRAS mutation status." (PMID 26471290, 2015). "Molecular biological analysis of the 93 patients with adenocarcinoma showed 59 epidermal growth factor receptor (EGFR) mutations (63.4%), five KRAS mutations (5.4%) and four EML4-ALK rearrangements (4.3%)." (PMID 25621070, 2015). "In the present study, EGFR mutation was observed only in the patients with adenocarcinoma (40/145 cases; 27.6%)." (PMID 24498965, 2014). "We aimed at investigating the outcomes of female patients with stage IIIB-IV adenocarcinoma of the lung according to EGFR and K-Ras mutational status." (PMID 25300933, 2014). "Distinct activating in EGFR and activation of associated signaling pathways is a well-established finding in upto 20% of adenocarcinoma located in the lung and tyrosine-kinase inhibitors (TKI) directed against the EGFR have entered clinical practice." (PMID 24593867, 2014). "The frequency of EGFR mutation in nGGOs in this study was 54.8%, which was relatively high in comparison to other, large cohorts of adenocarcinoma." (PMID 24885886, 2014). "Six ALK rearrangement-positive (ALK-positive) nGGOs were invasive adenocarcinomas, whereas 11.8% (14 out of 119) of EGFR mutation-positive nGGOs were pre-invasive or minimally invasive adenocarcinomas." (PMID 24885886, 2014).
adenocarcinoma (continued). "Pericardial biopsy revealed adenocarcinoma of lung primary, immunohistochemistry (IHC) and molecular testing for epidermal growth factor receptor (EGFR) mutation and anaplastic lymphoma kinase (ALK) rearrangement were negative." (PMID 26237019, 2014). "The current study reports a 77-year-old patient diagnosed with adenocarcinoma harboring L858R and T790M point mutations in the EGFR gene." (PMID 25120654, 2014). "EGFR-TKIs are therefore good candidates for first-line post-recurrence treatment in resected adenocarcinoma patients with distant metastases, but only in those with EGFR mutations." (PMID 24944713, 2014). "Sequence alterations of TSC1 were found in only one cell line, i.e. the “HCC827” cells, i.e. an adenocarcinoma cell line harboring an acquired mutation within the EGFR tyrosine kinase domain." (PMID 24593867, 2014). "Until now, the major focus has been identification of EGFR mutated adenocarcinomas that respond to TKI." (PMID 25763322, 2014). "Women are more susceptible to the carcinogenic effects of cigarettes and have more adenocarcinoma and EGFR mutations." (PMID 25474743, 2014). "It is of interest to note that Asian NSCLC patients who had ALK rearrangements shared similar features to those with EGFR mutations in terms of gender, smoking status and adenocarcinoma." (PMID 24959902, 2014). "Univariate analysis showed that adenocarcinoma histology, EGFR mutations, and blood MUC1 and VEGF mRNA positivity were associated with PFS." (PMID 25410981, 2014). "With the discovery of epidermal growth factor receptor (EGFR) and the development of gefitinib and erlotinib, which can target therapy in EGFR mutations, the lifetime and quality of life of adenocarcinoma patients have greatly improved." (PMID 24743427, 2014). "Blood samples from 23 patients with adenocarcinoma of NSCLC that carried tyrosine kinase inhibitor-sensitizing EGFR mutations were taken immediately before treatment with erlotinib." (PMID 25103305, 2014). "The logistic regression analysis revealed that the female gender, adenocarcinoma, distant metastasis and chemotherapy are factors associated with EGFR gene mutation (P<0.05)." (PMID 25013503, 2014). "The total EGFR gene mutation rate was marginally higher than that reported in previous studies, however, the majority of mutations were detected in adenocarcinoma, which is consistent with previously reported results." (PMID 25013503, 2014). "ALK fusion has also been found in older patients, smokers, patients with EGFR mutation and non-adenocarcinoma histological subtypes, such as adenosquamous carcinoma and large cell carcinoma." (PMID 24404167, 2014). "While it is known that EGFR-TKIs, including erlotinib, mainly benefit EGFR-mutated adenocarcinomas, a pooled analysis was conducted that demonstrated an efficacy of gefitinib for non-adenocarcinoma NSCLC patients harboring the EGFR mutation." (PMID 24527088, 2014). "Patients of East-Asian origin with adenocarcinoma have been shown to be significantly associated with a favorable response to EGFR TKIs." (PMID 25202368, 2014). "Repeat cytology of her right pleural fluid showed adenocarcinoma with an EGFR exon 19 deletion and a second mutation of T790M associated with EGFR-TKI resistance." (PMID 24555578, 2014). "Recent studies have suggested that the presence of pulmonary metastasis and malignant pleural effusion is predictive of EGFR mutations, as is the case in adenocarcinoma." (PMID 25364452, 2014). "Though mutations in EGFR are thought to be a driver in adenocarcinomas, it is possible that TTF-1 (being a transcription factor) facilitates the transcription of necessary genes to maintain survival signaling and evade apoptosis." (PMID 25594059, 2014). "In summary, the present study revealed that the EGFR mutation, L747S, was detected in male smokers with >30 pack-years each, and who were diagnosed with adenocarcinoma, squamous cell carcinoma and SCLC." (PMID 24396447, 2014).